CXCR3 (C-X-C motif chemokine receptor 3)
Diseases named in the same sentence as CXCR3 in open-access papers (continued):
Sharing a sentence is not in itself a finding about the gene and the disease.
melanoma (continued). "In a murine model of metastatic-like melanoma, engraftment was coordinate with CXCR3+ monocyte/macrophage accumulation in the lungs and was sensitive to pharmacologic inhibition of CXCR3 signaling." (PMID 28358049, 2017). "Upregulated CXCR3 expression in human breast, melanoma, renal and colon tumors correlates with poor prognosis." (PMID 29050279, 2017). "Of the many chemokines that CD8+ T-cells can respond to, those that signal through the CCR5 and CXCR3 axes are suggested to be the most important in recruiting CD8+ T-cells into melanoma." (PMID 28435677, 2017). "We have recently shown a strategy to enhance the migration of CXCR3-positive human NK cells to melanoma tumors by stimulating local CXCL10 secretion as CXCR3 ligands are not usually present at the tumor site." (PMID 28923105, 2017). "We earlier reported that CXCR3 expressed on melanoma and CRC cells promoted their metastases to the draining lymph nodes where CXCL9/10, ligands of CXCR3, are expressed at high levels." (PMID 27136535, 2016). "Increased expression of the chemokine receptor, CXCR3, on melanoma cells is correlated with increased metastasis and poor patient outcomes, suggesting a role for CXCR3 in the RGP to VGP transition." (PMID 25798946, 2015). "We found notable but variable (5–40%) expression of CXCR3 on the four human VGP melanoma cell lines tested; VMM12, VMM5, and two VMM5 clones, C4 and C9." (PMID 25798946, 2015). "The CXCR3 ligands, CXCL9 and CXCL10, within the LNs of host mice have facilitated metastasis of murine melanoma cells through CXCR3." (PMID 25798946, 2015). "Previous studies have demonstrated that knock down of constitutive expression of CXCR3 in a VGP murine melanoma cell line decreases metastatic frequency to adjacent lymph nodes." (PMID 25798946, 2015). "The increased expression of CXCR3 has been correlated with poor prognosis in breast, melanoma, colon, and renal cancer patients." (PMID 26485767, 2015). "We used flow cytometry to determine CXCR3 surface protein levels in human melanoma cell lines grown under normal culture conditions (media with 10% fetal bovine serum, incubated at 37°C with 5% CO2)." (PMID 25798946, 2015). "Activation of CXCR3 signaling was reported to promote tumor growth of glioma and basal cell carcinoma cell lines and to enhance invasion of melanoma and colorectal carcinoma cells." (PMID 25415223, 2014). "Addition of anti-CXCL9 or anti-CXCR3 antibodies to the co-cultures delayed the TEM of melanoma cells." (PMID 21179030, 2011). "This was also confirmed by the fact that the monolayer breakdown was blunted when the soluble chemokine was neutralised with anti-CXCL9 antibody or when the melanoma cells were pretreated with anti-CXCR3 antibody." (PMID 21179030, 2011). "CXCR3 expression in human and murine melanoma cell lines has been suggested by others to mediate directional cell migration along the chemokine gradients of CXCL9, CXCL10 and CXCL11." (PMID 21179030, 2011). "Taken together, these data demonstrate that human melanoma cells express the chemokine receptor CXCR3 not only within the tumour tissue, but also even after isolation and cultivation." (PMID 21179030, 2011). "Alternatively, the melanoma cells were co-cultivated with human ECs, stained with anti-CXCR3 (Alexa-488) and anti-CD144 (Alexa-633) antibodies and subsequently investigated using confocal laser scanning microscopy." (PMID 21179030, 2011). "We also found that the receptor for these ligands, that is, the CXCR3 protein, was expressed in all isolated, living melanoma cells." (PMID 21179030, 2011). "In mouse and human melanoma, a triple-positive (CXCR3+CCR5+CXCR6+) T-cell subset is essential for tumor control, and its genetic signature correlates with positive clinical response, while a distinct CCR5+CXCR6+ subset drives liver immune-related adverse events (IRAEs)." (PMID 41415437, 2025).
melanoma (continued). "Notably, elevated CXCR3 expression in melanoma, colon, and breast cancers is indicative of more malignant and aggressive tumor characteristics." (PMID 38275412, 2024). "This study also found that the CXCR3/CXCL9 axis enhances melanoma cell adhesion and may therefore also promote melanoma cell proliferation, survival and apoptosis." (PMID 37170733, 2023). "PD-L1+CXCR3+ cells majorly mediate the metastasis of melanoma and colon carcinoma." (PMID 36726488, 2023). "Cxcr3 was shown to promote CD8 T cell migration in B16 melanoma and other s.c tumor models." (PMID 36472588, 2023). "Therefore, strategies targeting CXCR3 to boost cytotoxic T lymphocyte recruitment should be carefully designed to avoid the hijack of melanoma cells." (PMID 35145233, 2022). "On the other hand, the dominant role of the CXCR3 pathway in regulating effector T cell infiltration in melanoma might mask the contributions of other chemokines which GPR182 regulates." (PMID 35013216, 2022). "For example, melanoma cells expressing CCR9 are often expected to metastasize in the intestine, CCR6 or CXCR4 in lung and liver, CCR4 associated with brain metastases, whereas cells with high expression of CCR10, CCR7, and CXCR3 populate regional lymph nodes." (PMID 35011682, 2021). "Melanoma with low expression of ligands for CXCR3 is poorly infiltrated by T cells." (PMID 33466646, 2021). "Furthermore, melphalan-exposed melanoma cells triggered upregulation of CXCR3, CCR4, CCR5 and PD-1 on co-cultured T cells and/or NK cells." (PMID 32002296, 2020). "However, chemokine receptor expression by transcriptome analysis in the TCGA melanoma data set revealed that high intratumoral content of CXCR3, CCR5 and PD-1 were significantly beneficial in terms of overall survival." (PMID 32002296, 2020). "Similarly, in a B16 melanoma mouse model, the deletion of CXCR3 in CTLs lead to an impaired anti-tumoral response due to the failure of CTL infiltration in the TME upon anti-PD-1 treatment, suggesting CXCR3-dependent anti-PD-1 based anti-tumoral response." (PMID 31216755, 2019). "Their homing to melanomas, where they mediated growth regression, was dependent on CXCR3 as CXCR3-deficient NK cells failed to migrate into melanoma." (PMID 30899263, 2019). "The machinery driving the colonization by melanoma cells of metastatic sites, including the bone, has been poorly investigated although previous studies correlated the CXCR3, CXCR4, CCR7 and CCR10 expression with the enhanced propensity to migrate to lymph nodes, lung and skin." (PMID 31324252, 2019). "In another study, melanoma (B16F10) or breast cancer (E0771) cells injected in CXCR3−/− mice showed a significant increase in tumor growth compared to wild type (WT) mice, which was associated with a lower prevalence of CD8+ and CD4+ T cells as well as NK cells." (PMID 31216755, 2019). "Similarly, we found that activated CXCR3 positive human NK cells selectively migrated towards CXCL10 positive human melanoma tumors in an in vivo xenograft model." (PMID 31340613, 2019). "Interestingly, although CXCR3 expression correlates with a worse clinical outcome in melanoma, colon cancer, chronic B-cell lymphocytic leukemia, and renal cell carcinoma, reduced expression of CXCR3 in breast cancer has been associated with shorter survival." (PMID 30591657, 2018). "This last observation suggests that (i) CXCR3 is potentially downregulated due to a negative feedback loop of cell regulation following STAT3 activation or (ii) these CXCR3+ T cells, which are underrepresented in the periphery, are actually localized to melanoma lesions." (PMID 30420855, 2018). "Based on our initial data, we hypothesized a pivotal role for hematopoietic expression of CXCR3 for mediating melanoma engraftment in lung." (PMID 28358049, 2017).
melanoma (continued). "Expression of CXCR3 on circulating T cells or its chemokine ligands, CXCL9 and CXCL10, in tumor tissues has been reported to be associated with elevated intratumoral T cell infiltration in melanoma and colorectal cancer patients." (PMID 28407741, 2017). "In addition to CRC, CXCR3 was also reported to be correlated with a poor prognosis in breast cancer and melanoma." (PMID 27136535, 2016). "Implications: Expression of CXCR3 on BRAFWT melanoma cells may be a mediator of melanoma progression." (PMID 25798946, 2015). "It is important to consider that in other tumor types such as breast cancer and melanoma, IP-10 may drive an anti-tumoral response by recruiting CXCR3+ Th1 lymphocytes." (PMID 25415223, 2014). "Moreover, the receptors CXCR3, CXCR4, CCR7 and CCR10 have been implicated in the process of metastasis in melanoma, based on studies with animals." (PMID 24559071, 2014). "Indeed, it has been shown that mouse melanoma B16F10 cells constitutively express CXCR3, and its ligands CXCL9/Mig, CXCL10/IP-10, and CXCL11/I-TAC induce cellular responses in vitro, such as actin polymerization, migration, invasion, and cell survival." (PMID 24559071, 2014). "Simultaneous expressions of CXCL10 and CXCR3 in breast cancer cell lines additionally lead to CXCL10-dependent proliferation of CXCR3-positive cells and treatments using CXCR3 antagonists, and ligand-neutralizing antibodies inhibit metastasis in melanoma and breast cancer in mice." (PMID 24395654, 2014). "Analysis of lymph node metastases revealed high expression of CXCR3 in melanoma cells, which could also be observed in ECs isolated from both normal skin and tumour tissue." (PMID 21179030, 2011). "However, genetic deletion of CXCR3 or in vivo administration of anti-CXCR3 mAbs has been shown to enhance bone marrow NK cell infiltration, improving anti-myeloma efficacy and promoting tumour rejection in melanoma models." (PMID 40361472, 2025). "Additionally, CXCR3 plays a key role in transplant rejection, metastasis of melanoma and colon cancer, and may act as a co-receptor for certain HIV strains." (PMID 40786052, 2025). "In addition, several evidences reveal that CXCR3 on tumor cells surface facilitates the proliferation and metastasis of a variety of malignancies, including colon cancer and melanoma, and CXCR3 blockade has shown a prospective anti-metastatic potential in breast cancer." (PMID 38264648, 2023). "We found that CXCR3 pathway activation can not only predict the effectiveness of ICIs in patients with metastatic urothelial carcinoma, but it can also predict the effectiveness of immunotherapy in patients with melanoma, non-small cell lung cancer, and liver cancer." (PMID 35562800, 2022). "And the negative correlation between 6 ICD-related genes (CD8A, PRF1, IFNG, CXCR3, TNF, CD8B) and risk score and the protective function of these 6 genes in SKCM indicates that drugs targeting these genes may be a novel treatment method in melanoma." (PMID 36211436, 2022). "The CXCL9, CXCL10, and CXCL11/CXCR3 axis was generally considered to have antiangiogenic effects on endothelial cells and has been reported as effective tumor angiogenesis inhibitors in some in vivo tumor models, including pancreatic cancer, breast cancer, lung cancer, and melanoma." (PMID 32685487, 2020). "Moreover, we have previously found an enrichment of CXCR3-expressing CD4+ T cells in metastatic lymph nodes compared with circulating T cells perhaps explaining the differences found in the blood between melanoma patients and healthy volunteers." (PMID 30420855, 2018). "Thus, we present a new role for CXCR3 in the process of melanoma engraftment." (PMID 28358049, 2017). "Conversely, increased MIG could facilitate melanoma cell metastasis through CXCR3." (PMID 27556503, 2016).
melanoma (continued). "Our results suggest that, in BRAFWT melanomas, increases in CXCR3 signaling mediates increases in IL-8 expression, and consequently, that CXCR3 may contribute to the transition from RGP to VGP in the melanoma patient population where the BRAFV600E mutation is not present." (PMID 25798946, 2015). "Penetration of melanoma cells could be significantly decreased when CXCL9 was preincubated with anti-CXCL9 antibody or when the melanoma cells were treated with anti-CXCR3 antibody for 1 h before the challenge of the EC monolayer." (PMID 21179030, 2011). "To assess whether CXCR3 is also expressed by melanoma cells in metastatic tumour tissues, we performed immunofluorescence and confocal microscopy from normal skin and melanoma metastases, using anti-CXCR3 (Alexa-488) antibody, anti-CD144 (Alexa-633) antibody and phalloidin-568." (PMID 21179030, 2011). "Moreover, CXCR3 expression is higher in melanoma cells than in ECs." (PMID 21179030, 2011). "Additionally, the organ-specific effect of CXCR3 blockade has also been observed in melanoma." (PMID 19436305, 2009). "Similar results were obtained in a mouse melanoma model, showing that IFN-β stimulates the expression of the ligands CCL5 and CXCR3 and induces tumor infiltration by T-lymphocytes." (PMID 41373826, 2025). "Metacluster C58748 represented CD4+CD45RO+ T cells that expressed CCR6, CCR7, CXCR3 and CXCR5 suggesting TFH cells in melanoma which exhibit elevated CEACAM1 levels in the context of treatment-resistant compared to treatment-naive disease." (PMID 38956268, 2024). "A previous in vitro study showed moderate CXCR3 expression in a human melanoma cell line (BLM), lower expression in amelanotic cutaneous melanoma cell line (SK‐Mel 37) and low expression in human malignant melanoma cell lines, such as MeWo and A375 cells." (PMID 37170733, 2023). "Naama Margolis and colleagues found that ADAR1 regulates the production of chemokines in melanoma, such as CCR4, CCR5, and CXCR3, in melanoma to recruit T lymphocytes." (PMID 37217462, 2023). "The major chemokine/chemokine receptor interactions occurring in melanoma development and progression include the CXCR4/CXCR7/CXCL12, CXCR3/CXCL9,10,11, CXCR1,2/CXCL8, CCR2/CCL2, CCR4/CCL17,22, CCR5/CCL5, CCR7/CCL21 and CCR10/CCL27 axes." (PMID 37170733, 2023). "CXCR3 is widely expressed in melanoma cell lines, and CXCL9 stimulation promotes melanoma cell migration." (PMID 36479091, 2022). "Simultaneous reduction of CXCR3, CXCL9, and/or CXCL10 expression suppresses cancer metastasis rates in melanoma, CRC,310 and breast cancer models." (PMID 35702353, 2022). "determined that CXCL10/CXCR3 coexpression increased tumor cell metastasis and recurrence in both in vitro and in vivo analyses of B16F1 melanoma." (PMID 35702353, 2022). "Focusing on the chemokine receptor CXCR3, its expression on stage III melanoma patients’ peripheral or tumor-involved lymph node CD8 T cells improves survival." (PMID 36429101, 2022). "In the TME of a mouse melanoma model, exogenous supplementation of CXCL9/10 can assist PD-1 antibody in inhibiting tumor growth by increasing the proportion of CXCR3+ T cells." (PMID 36479091, 2022). "The same observation was made in a melanoma BM model where astrocytes secrete CXCL10, promoting migration of melanoma BM cells expressing CXCR3, the CXCL10 receptor." (PMID 35884845, 2022). "The chemokines that signal through CXCR3, including CXCL9 and CXCL10, have been suggested to promote T-cell infiltration and activation in melanoma and other solid tumors." (PMID 34203869, 2021). "Clinical data further confirm CCR5 and CXCR3 expression on T cells to correlate with CTL recruitment and a favourable outcome in melanoma in patients." (PMID 33809369, 2021). "We also observed that the expression of CXCR3, CCR4 and CCR5 was significantly higher on T cells and NK cells in peripheral blood of melanoma patients than in healthy controls." (PMID 32002296, 2020).
melanoma (continued). "CXCR3 along with CCR5 expression correlates with CD8+ T cell recruitment and favorable outcome in melanoma." (PMID 30405637, 2018). "CXCR3 and CCR5 has been shown to be the major chemokine receptor involved in CD8+ T cell infiltration in melanoma." (PMID 30405637, 2018). "The gradient established by these cells could act as a signal in circulation and the presence of CXCR3 expression in the host could facilitate recruitment of circulating macrophages and monocytes, which in turn could permit the successful engraftment of melanoma cells in the lung." (PMID 28358049, 2017). "Given the constitutive phosphorylation of ERK in BRAFV600E melanoma cells, it is possible that the ERK-mediated IL-8 expression in these cells is already too saturated to be affected by CXCR3 signaling." (PMID 25798946, 2015). "We have evaluated, using flow cytometry, the expression of the chemokine receptors CXCR4, CXCR3, CXCR7, CCR7 and CCR10, at cell surface and intracellular levels, for thirteen human melanoma cell lines." (PMID 24559071, 2014). "Besides colon carcinoma and melanoma, mammary tumour cells were also reported to express CXCR3 that facilitates the development of lung metastasis; therefore, suggesting that CXCR3 may be an important mediator for tumour cells dissemination to the lung." (PMID 19436305, 2009). "Protein expression of CXCR3 was detected by western blotting in human HT29 cells as well as in murine C26 cells; B16F10 melanoma cells providing a positive control of CXCR3 protein expression." (PMID 19436305, 2009). "To evaluate the significance of the direct effect of CXCL10-Fc on the ability of CXCR3+ CD4+ T cells to limit tumor growth, we performed an adoptive transfer in which CD4+ T cells were isolated from OT-II mice engrafted with Ret melanoma, transferred into CXCR3KO mice." (PMID 39474427, 2024). "Lastly, we evaluated the expression of CXCR3 in Pmel-1 T cells where a previous study showed a nonredundant role for CXCR3 in trafficking of murine and human T cells in melanoma during adoptive cell therapy." (PMID 38881188, 2024). "We and others have previously reported that CXCL10/CXCR3 signaling plays critical roles in melanoma tumor cell motility and metastases to the bone, lung, and brain, accompanied with elevated CXCL10 levels in a mouse model of spontaneous melanoma metastasis." (PMID 39268223, 2024). "We employed machine learning algorithms to screen six genes, BATF, CXCR3, GIMAP5, GPR8, IGHM, and ISG20, that have been extensively investigated in other cancers, including lymphoma, melanoma, leukemia, breast cancer, multiple myeloma, hepatocellular carcinoma, and lung cancer." (PMID 39559348, 2024). "Antisense RNA targeting of CXCR3 during cancer treatment with immunosuppressive agents inhibits the metastasis of B16F10 melanoma to lymph nodes but does not affect the possibility of tumor metastasis to the lung." (PMID 36479091, 2022). "Besides revealing macrophages, some researchers have found that CXCL10 activates its receptor CXCR3 to induce the infiltration of CD8+ T cells in colorectal cancer, breast cancer, melanoma." (PMID 35083488, 2022). "In melanoma, NK cells are recruited by the inflammatory chemokines CCL5 and CXCL9-11, expressed within the TME, by the engagement of the cognate receptors CCR5 and CXCR3, respectively." (PMID 34712615, 2021). "The disparity between the studies both within pancreatic cancer and between other types of solid tumors such as melanoma is not known, but it is possible that CXCR3 and its ligands affect malignant cells differently in various types of cancer." (PMID 34203869, 2021). "Four of these Top HRLs are recognized by 2 of the Top HRs and represent ligand-receptor pairs that have been previously identified as crucial mediators of T and B cell trafficking in melanoma: CXCL10 and CXCL9 are ligands for CXCR3; and CCL4 and CCL5 are ligands for CCR5." (PMID 34454518, 2021).